ENSG00000206776
Synonyms: LOC124900266
Gene: Small nucleolar RNA gene on chromosome 8 (119,388,348 to 119,388,469, forward strand). Ensembl gene ENSG00000206776.
Gene Ontology:
Biological process: RNA processing
Cellular component: nucleolus
Homologues: Orthologues: rat LOC120095737 (75% identical), rat Snora32 (67% identical), rat LOC120097588 (62% identical), rat LOC120102640 (52% identical), rat LOC120100386 (45% identical), rat LOC120098685 (41% identical). Paralogues in human: SNORA32 (84% identical).